TLN1 (talin 1)
Diseases named in the same sentence as TLN1 in open-access papers (continued):
Sharing a sentence is not in itself a finding about the gene and the disease.
nasopharyngeal carcinoma (7 papers, 2015 to 2023). A carcinoma arising from the nasopharyngeal epithelium. "Previous studies conducted on oral squamous cell carcinoma (OSCC) and nasopharyngeal carcinoma have shown that increased expression of the talin-1 protein leads to the progression of the disease and poor survival." (PMID 37942198, 2023). "For example, miR-429 can inhibit the proliferation, migration and invasion of nasopharyngeal carcinoma cells by inhibiting TLN1 expression." (PMID 35468721, 2022). "The aim of this study was to evaluate the expression and prognostic value of Talin-1 in nasopharyngeal carcinoma (NPC)." (PMID 25925041, 2015).
melanoma (6 papers, 2010 to 2024). A malignant, usually aggressive tumor composed of atypical, neoplastic melanocytes. "Furthermore, higher expression levels of Talin-1 associated with an increase in the stage of melanoma, showing the probable potential of Talin-1 for risk assessment in melanoma patients." (PMID 37013489, 2023). "However, upregulation of Talin-1 was significantly associated with melanoma recurrence after tumor resection in our study." (PMID 37013489, 2023). "Furthermore, overexpression of Talin-1 was associated with higher stages, local invasion, and recurrence of melanoma, emphasizing the role of cytoskeletal adhesion and signaling in melanoma progression and invasion." (PMID 37013489, 2023). "Total protein lysate analysis revealed significantly higher levels of endogenous Talin-1 in HFF cells compared to melanoma cells, suggesting a potential correlation between Talin-1 expression and FA characteristics." (PMID 39086658, 2024). "Of particular interest, total protein lysates extracted from HFF cells revealed significantly higher levels of endogenous Talin-1 compared to those obtained from melanoma cells." (PMID 39086658, 2024). "Higher expression levels of Talin-1 were observed in skin tumor tissues compared to normal tissue samples (melanoma and NMSC tissues)." (PMID 37013489, 2023). "We used Kaplan–Meier survival analysis to compare DSS or PFS based on Talin-1 expression (H-score) in melanoma and NMSC patients." (PMID 37013489, 2023). "The evaluation of the staining pattern in melanoma and NMSCs exhibited differential expression of Talin-1 protein with a range of intensities from weak to strong." (PMID 37013489, 2023). "The role and clinical significance of Talin-1 protein in melanoma and NMSCs remain unexplored." (PMID 37013489, 2023). "Our results highlighted upregulation of Talin-1 in melanoma progression and LVI." (PMID 37013489, 2023). "The expression of Talin-1 protein in melanoma invasion has not been investigated prior to our study, although many studies have reported the involvement of proteins associated with Talin-1 in melanoma progression." (PMID 37013489, 2023). "Furthermore, experimental expression of Talin-1 protein through IHC method indicated a significant difference in cytoplasmic expression of this protein in melanoma and NMSC tumor cells compared to normal skin tissue." (PMID 37013489, 2023). "Moreover, there was a statistically significant difference between the cytoplasmic expression of Talin-1 protein in melanoma and NMSCs tissues." (PMID 37013489, 2023). "The results showed that there is a statistically significant difference in Talin-1 expression in terms of intensity of staining, percentage of positive tumor cells, and H-score in melanoma tissues compared to NMSC samples (P = 0.001, P < 0.001, and P < 0.001, respectively)." (PMID 37013489, 2023). "In addition, there was a statistically significant difference in Talin-1 expression in terms of intensity of staining, percentage of positive tumor cells, and H-score in melanoma tissues compared to NMSC (P = 0.001, P < 0.001, and P < 0.001, respectively)." (PMID 37013489, 2023). "Moreover, our results exhibited differential expression of Talin-1 protein between melanoma and NMSCs tissues with a statistically significant difference between the two groups, which may affect their prognosis and treatment options." (PMID 37013489, 2023). "The mentioned evidence implies Talin-1 is a crucial player in the integrin activation process and may have a promotive effect on malignant melanocytes, which may be hijacked in invasive melanoma by upregulating its expression for tumor invasion and progression." (PMID 37013489, 2023). "In the current study, we observed a positive correlation between Talin-1 expression and LVI in melanoma skin cancer tissues." (PMID 37013489, 2023).
melanoma (continued). "As one of the main molecules in Talin-1 dependent integrin signaling and FA assembly, FAK plays a substantial role in PI3K/AKT signaling pathway, which is an important oncogenic pathway and therapeutic target in melanoma and NMSCs." (PMID 37013489, 2023). "Talin-1 was evaluated in 106 skin cancer (33 melanomas and 73 non-melanomas skin cancer (NMSC)) and 11 normal skin formalin-fixed paraffin-embedded (FFPE) tissue samples using immunohistochemical technique on tissue microarrays (TMAs)." (PMID 37013489, 2023). "In our investigation, we employed fluorescently tagged Talin-1 to visualize FA structures, facilitating the subsequent assessment of FA and cell morphology variations among three melanoma lines (Meljuso, A375P, and A2058) and a non-transformed cell line, human foreskin fibroblast (HFF)." (PMID 39086658, 2024).
ovarian carcinoma (6 papers, 2016 to 2025). A malignant neoplasm originating from the surface ovarian epithelium. "MS-275, a HDAC inhibitor, inhibits the tumor spheroid formation of ovarian cancer cells and impacts on Talin‐1‐α5β1‐integrin‐mediated actin cytoskeleton and extracellular matrix protein remodeling." (PMID 40093794, 2025). "PHB, SRC, talin-1, tubulins and WDR1 are related to development of ovarian cancer resistance to paclitaxel and cis-platin." (PMID 29344361, 2018). "Published proteomics and molecular biology studies suggest up-regulation of ACTN4, CRKL, GELS, HSPA8, talin-1, tubulins and WDR1 in ovarian cancer." (PMID 29344361, 2018).
ovarian serous carcinoma (6 papers, 2015 to 2023). "The present study aimed to assess expression and prognostic significance of the talin-1 protein in ovarian serous carcinoma (OSC) patients." (PMID 37942198, 2023). "Expression of Talin-1 (Intensity of staining, percentage of positive tumor cells, and H-score) in the ovarian serous carcinoma (OSC), benign ovarian tumors, and normal tissue samples." (PMID 37942198, 2023). "Treatment with miR-9 for ovarian serous carcinoma cells suppressed their migratory and invasive capabilities by targeting TLN1 and downregulating its expression." (PMID 34732818, 2021).
atherosclerosis (5 papers, 2019 to 2022). A disease characterized by the build-up of fatty material and calcium deposition in the arterial wall resulting in partial or complete occlusion of the arterial lumen. "Regarding the association between talin-1 and atherosclerosis, TLN1 expression was demonstrated to be downregulated in atherosclerotic plaques." (PMID 32566035, 2020). "Through analysis of the public database, seven hub genes (UQCR11, UBE2N, ADD1, TLN1, IRAK3, LY96, and MAP3K1) have recently been found to be strongly associated with familial hypercholesterolemia and contribute to a higher risk of atherosclerosis." (PMID 34895070, 2021). "Our study identified seven core genes (UQCR11, UBE2N, ADD1, TLN1, IRAK3, LY96, and MAP3K1) that are strongly linked to FH and lead to a higher risk of atherosclerosis." (PMID 32760426, 2020). "They suggested that talin-1 downregulation causes the loosening of cell-ECM interactions, thereby leading to the injury and disintegration of vascular walls in atherosclerosis." (PMID 32566035, 2020). "If Talin-1 can highly change the stability of the plaque through some pathways, and a number of new drug targets need to be provided for stabilizing the atherosclerosis plaque." (PMID 31215474, 2019). "Since inflammation plays a role in atherosclerosis, high plasma talin-1 concentrations in CAD patients may reflect inflammation and atherosclerosis in the coronary arteries." (PMID 36135831, 2022). "In this study, by detecting the content of Talin-1 in stable and unstable atherosclerosis plaque samples, we found that the low-expression of Talin-1 may result in instability of plaque." (PMID 31215474, 2019). "The TLN1 expression level in atherosclerotic plaques is significantly reduced, and it plays a central role in cell adhesion, indicating that tissue disintegration in atherosclerosis may be partly induced by TLN1 downregulation, leading to cell-ECM interaction loosening and tissue reorganization." (PMID 32760426, 2020).
colon cancer (5 papers, 2020 to 2025). "A study on colon cancer demonstrated a significant correlation between increased expression of talin-1 and tumor grade, The TNM Classification of Malignant Tumors (TNM) stage, and lymph node metastasis." (PMID 37942198, 2023). "P-selectin recruited talin-1 to its cytoplasmic tail and this led to an activation of integrin GPIIb/IIIa, an infiltration of platelets into insulinoma or colon cancer tissue." (PMID 33805059, 2021).
coronary artery disease (5 papers, 2015 to 2025). "In fact, high FGB levels are associated with an increased risk of coronary artery disease and the pathogenesis of myocardial infarction, and TLN1 participates in the establishment of focal cell to cell adhesions, which are characteristic in the pro-thrombotic and inflammatory process." (PMID 26152126, 2015). "However, we have recently reported high concentrations of plasma talin-1 in patients with coronary artery disease (CAD)." (PMID 36135831, 2022). "Recently, we reported high concentrations of plasma talin-1 in patients with coronary artery disease (CAD)." (PMID 36135831, 2022). "Both miR-182-5p and miR-9-5p were highly expressed in patients with coronary artery disease (CAD) and they both downregulated the TLN1 gene." (PMID 36012267, 2022). "However, talin-1 levels in the blood of patients with atherosclerotic diseases, such as coronary artery disease (CAD), have not been elucidated yet." (PMID 32566035, 2020). "However, blood levels of soluble talin-1 (sTalin-1) in patients with atherosclerotic disease, such as coronary artery disease (CAD), have not been elucidated." (PMID 32566035, 2020).
glioma (5 papers, 2015 to 2025). A benign or malignant brain and spinal cord tumor that arises from glial cells (astrocytes, oligodendrocytes, ependymal cells). "Key hub genes such as TLN1, FN1, and IRF7 were associated with glioma progression and poor prognosis." (PMID 40365337, 2025). "Then, we determined the effect of TLN1 in glioma migration/invasion." (PMID 26336988, 2015). "In addition, TLN1 was significantly overexpressed in glioma specimens, and its expression correlated with poor survival of glioma patients, determined by Rembrandt databases." (PMID 26336988, 2015). "TLN1 and TPM2 are key regulators of cytoskeletal dynamics and cell-matrix interactions, directly promoting glioma cell migration and invasion." (PMID 40365337, 2025). "KALRN, EIF1AD, DLL1, SH3RF1, and TLN1 are involved in neuronal structural integrity, plasticity, differentiation, and may contribute to the highly invasive nature of GBM as compared to other gliomas." (PMID 36834486, 2023).
triple-negative breast carcinoma (5 papers, 2015 to 2026). An invasive breast carcinoma which is negative for expression of estrogen receptor (ER), progesterone receptor (PR), and human epidermal growth factor receptor 2 (HER2). "TLN1 upregulation is associated with poor disease-free survival (DFS) in triple-negative breast cancer (TNBC)." (PMID 35285795, 2022). "Silencing TLN1 reduces triple-negative breast cancer (TNBC) cell motility by blocking epithelial-mesenchymal transformation (EMT)." (PMID 35285795, 2022). "In addition, kinesin family member 14 (KIF14) and TLN-1 expression levels predict a better outcome after cytotoxic chemotherapy, and inhibition of these genes sensitizes triple-negative breast cancer (TNBC) cells to therapeutic intervention." (PMID 26822056, 2016). "Interestingly, KIF14 and TLN-1 inhibition was found to sensitize triple-negative breast cancer (TNBC) cells to therapeutic intervention." (PMID 26822056, 2016). "Furthermore, higher expression of Talin-1 was observed in triple-negative breast cancer cell lines, and low Talin-1 expression was a prognostic marker for better outcome after cytotoxic chemotherapy." (PMID 25925041, 2015).
Aortic dissection (4 papers, 2017 to 2024). Aortic dissection refers to a tear in the intimal layer of the aorta causing a separation between the intima and the medial layers of the aorta. "A study demonstrated that TLN1 was significantly downregulated in aortic tissue of patients with aortic dissection, and another case report showed rare missense variants in TLN1 associated with familial and sporadic SCAD cases." (PMID 39654947, 2024). "In addition, studies have shown that TLN1 was downregulated in aortic tissue of patients with aortic dissection, and rare heterozygous missense variants in TLN1 have been found in individuals with familial spontaneous coronary artery dissection." (PMID 39704176, 2024). "This variant was subsequently found in 10 cases of a large SCoAD cohort, thus, it is believed to have detrimental vascular effects, since TLN1 alteration has been also found in aortic dissection." (PMID 37214559, 2023). "Talin-1 was significantly downregulated in the media of aortic dissection samples compared with controls (P < 0.05)." (PMID 28637452, 2017). "This study aimed to assessed whether Talin-1 is involved in the pathogenesis of aortic dissection via regulating vascular smooth muscle cell (VSMC) biological function." (PMID 28637452, 2017).
cardiac hypertrophy (4 papers, 2020 to 2025). "Now, many TNF-dependent genes linked to ECM remodeling as well as AF are upregulated with exercise in WT atria compared to sedentary, including Mmp14, Fgf2 (i.e., fibroblast growth factor 2, which activates p38 and induces cardiac hypertrophy as well as fibrosis), Gsk3β, and Tln1." (PMID 33424629, 2020). "Moreover, a recent study showed that the absence of Tln1 in cardiac fibroblasts enhances ventricular hypertrophy during pressure overload." (PMID 40819162, 2025).
Coronary artery dissection (4 papers, 2020 to 2024). Acute occurrence of a dissection (tear within the tunica intima and entry of blood into the tunica media) of a coronary artery. "From the careful work of Turley and co-workers a genetic link between a talin-1 variant, A2013T, and spontaneous coronary artery dissection (SCAD) was firmly established." (PMID 39163585, 2024). "Variants of talin-1 (TLN1) have recently been linked with spontaneous coronary artery dissection (SCAD) a condition where a tear can form in the wall of a heart artery necessitating immediate medical care." (PMID 39163585, 2024). "Since some TLN1 gene variants were reported to be associated with coronary artery dissection, such variants may have affected plasma sTalin-1 levels in our patients with CAD." (PMID 32566035, 2020).
COVID-19 (4 papers, 2020 to 2023). A disease caused by infection with severe acute respiratory syndrome coronavirus 2. "Plasma protease C1 inhibitor was upregulated in COVID-19 patients, displaying a positive correlation, while FIBA, talin 1, filamin A, myosin heavy chain 9 and the beta subunit of hemoglobin, displayed negative correlations." (PMID 33096722, 2020).
endometriosis (4 papers, 2021 to 2025). The growth of functional endometrial tissue in anatomic sites outside the uterine body. "In the current study, we found that Talin-1 expression at both mRNA and protein levels was significantly upregulated in the eutopic and ectopic endometrial tissues of endometriosis compared with the controls, suggesting that Talin-1 could be associated with the genesis and progress of endometriosis." (PMID 33750407, 2021). "Whether Talin-1 is associated with the pathophysiology of endometriosis remains unclear." (PMID 33750407, 2021). "Ma and Jiang proposed a distinct role for TLN1 in the pathogenesis of endometriosis, highlighting its involvement in the differentiation of regulatory T cells (Tregs)." (PMID 40072086, 2025). "The expression levels of both Talin-1 mRNA and protein are elevated in both ectopic endometrium and eutopic lining tissues in women with endometriosis in comparison to controls." (PMID 38398227, 2024). "Key influencers, like Talin-1, impact endometriosis cell migration, with its downregulation significantly impeding cell adhesion, invasion, and migration." (PMID 38398227, 2024). "We identified that the mRNA and protein of Talin-1 were highly expressed in the ectopic and eutopic endometrial tissues of patients with endometriosis compared to the control endometrium tissues." (PMID 33750407, 2021). "But it’s worth noting that the increase in the expression of Talin-1 in the ectopic endometrial tissues of patients with endometriosis was higher than that in eutopic endometrium." (PMID 33750407, 2021). "When tests were performed on the matched samples of eutopic and ectopic endometrium tissues of women with endometriosis, the expression of Talin-1 was significantly increased in the ectopic endometrium (P < 0.001)." (PMID 33750407, 2021). "This study was to investigate the expression level of Talin-1 in endometriosis and the role of Talin-1 in the proliferation, adhesion, migration, and invasion of human endometrial stromal cells (ESCs)." (PMID 33750407, 2021). "Our findings can provide insights into the possible role of Talin-1 in the genesis and progress of endometriosis." (PMID 33750407, 2021). "The downregulation of this protein led to the inhibition of the cells’ ability to adhere, invade, and migrate, indicating the key role that Talin-1 plays in the progression of endometriosis and may play a role in the EMT process." (PMID 38398227, 2024). "Thus, this study aimed to investigate the expression of Talin-1 in endometriosis and analyzed the potential role of Talin-1 in the development of endometriosis." (PMID 33750407, 2021). "The present findings provide novel insights into the role of Talin-1 in endometriosis." (PMID 33750407, 2021). "We showed that the expression of Talin-1 was elevated in women with endometriosis." (PMID 33750407, 2021). "Talin-1 can promote cell invasion, migration and adhension in various cancer cells, but its role in endometriosis has not been investigated." (PMID 33750407, 2021). "This study has several limitations, including lacking ESCs from women without endometriosis in parallel, lack of an established physiologic level of Talin-1 in ESCs, lacking ectopic ESCs experiments, and the possibility of off-target effects from siRNAs." (PMID 33750407, 2021). "However, the relationship between Talin-1 and endometriosis has never been reported." (PMID 33750407, 2021).
lung carcinoma (4 papers, 2018 to 2023). "We identified several CRC-associated proteins, e.g., FN1, HSPA8, and TLN1, in the blood plasma obtained from patients with lung cancer." (PMID 37241967, 2023). "The abundance of TLN1, TUBA4A, HSPA8, ITGB3, TSG101, and PACSIN2 in the plasma of lung cancer patients was measured using targeted mass spectrometry and compared to that in plasma from healthy volunteers." (PMID 34684727, 2021). "Together, these observations suggest that FN1, TLN1, ITGB3, HSPA8, and TUBA4A detection in the blood using SRM/SIS may serve as an indicator of tumors, and elevations in their concentrations coupled with PACSIN2 detection discriminate lung cancer from other malignancies." (PMID 34684727, 2021).